MIR935 (microRNA 935)
Synonyms: hsa-mir-935; MIRN935; mir-935
Gene: MicroRNA gene on chromosome 19 (53,982,307 to 53,982,397, forward strand). Ensembl gene ENSG00000284583.
Homologues: Orthologues: chimpanzee ptr-mir-935 (100% identical), macaque MIR935 (100% identical).